EPHB2 (EPH receptor B2)
Diseases named in the same sentence as EPHB2 in open-access papers (continued):
Sharing a sentence is not in itself a finding about the gene and the disease.
breast carcinoma (continued). "We are in the process of examining the impact of ephrin binding on the pro-autophagic function of EphB2 in breast cancer." (PMID 34360867, 2021). "In breast cancer, 82% (77/94) patients show moderate and strong EphB2 protein expression, and the increased level of EphB2 expression correlated with poor overall survival of patients." (PMID 32226496, 2020). "Cytoplasmic EPHB2 predicted shorter breast cancer survival and tended to indicate shorter metastasis-free survival in univariate analysis." (PMID 26870995, 2016). "While, high membranous EPHB2 indicated longer distant recurrence-free survival, H.R. (95%CI)=0.66 (0.41-1.05), P=0.08 and longer breast cancer survival, H.R. (95%CI)=0.47 (0.28-0.80), P=0.006." (PMID 26870995, 2016). "Membranous EPHB2 predicted longer breast cancer survival in both univariate and multivariate analysis while cytoplasmic EPHB2 indicated shorter breast cancer survival in univariate analysis." (PMID 26870995, 2016). "Although we found that EPHB2 was the most promising candidate in our breast cancer cohorts, EPHB2 together with EPHB6, EPHA2, EPHA4 and the ligands EFNB1 and EFNB2 were important to define prognostic relevant clusters." (PMID 26870995, 2016). "High cytoplasmic EPHB2 expression predicted shorter distant metastasis-free survival, H.R. (95%CI)=1.37 (0.92-2.04), P=0.12 and poor breast cancer survival, H.R. (95%CI)=1.52 (0.10-2.33), P=0.05." (PMID 26870995, 2016). "EPHB2, although poorly investigated, has shown to be a promising prognostic marker in breast cancer but more studies on its protein expression and localization are still encouraged." (PMID 26870995, 2016). "Especially EPHB2 predicted poor breast cancer survival in several materials and EPHB2 protein expression has also prognostic value depending on cell localization." (PMID 26870995, 2016). "High EphB2 expression was correlated with poor overall survival in breast cancer patients." (PMID 35223830, 2022). "The fact that high EphB2 levels associate with shorter DMFS suggests a new line of investigation, whereby EphB2 could be viewed as a predictor of metastatic progression, specifically in luminal types of breast cancer." (PMID 34360867, 2021). "However, there is another important but distinct aspect to the EphB2/ephrin-mediated role in breast cancer, the heterotypic communication between mammary cells and stromal/endothelial cells." (PMID 34360867, 2021). "The same finding was observed in the MCF10A-derived model of breast cancer progression, whereby both the invasive (CA1ACL1 and CA1DCL1) and the DCIS.com cell variants co-expressed higher levels of EphB2, EFNB1, and EFNB2 than the benign parental MCF10A cell line." (PMID 34360867, 2021). "We also found that higher EphB2 expression could be a prognostic factor for distant metastasis, specifically in the luminal subtypes of breast cancer." (PMID 34360867, 2021). "Cytoplasmic EPHB2, albeit indicating higher risk for breast cancer death and metastasis, was not an independent prognostic factor in multivariate analysis." (PMID 26870995, 2016). "Interestingly, membranous and cytoplasmic EPHB2 were negatively correlated indicating opposite patient prognosis: cytoplasmic EPHB2 accounted for shorter breast cancer survival and membranous EPHB2 for good prognosis." (PMID 26870995, 2016). "We also suggest that EFNB1 and EFNB2 could be additional interesting candidates and revealed the clinical value of EPHB2 as a potential prognostic marker in breast cancer." (PMID 26870995, 2016). "Multivariate Cox proportional hazard regression; adjusted for the well-known clinical variables ER, HER2, lymph nodes, tumor size and treatment; showed that membranous EPHB2 was an independent predictor of breast cancer-free survival in addition to lymph nodal status and tumor size." (PMID 26870995, 2016). "Independent studies reported EphB4 and EphB2 overexpression in human breast cancer." (PMID 21935409, 2011).
breast carcinoma (continued). "In the present study, we assessed the prognostic significance of expression of the EphB2 receptor and ephrin ligands in breast cancer, as a first exploration of the clinical validity of our hypothesis that ephrin ligands determine the pro- and anti-cancer roles of EphB2." (PMID 34360867, 2021). "Eb2Mab-12-mG2a and Eb2Mab-12-hG1 showed the antitumor effect against xenograft tumors of CHO/EphB2, TNBC breast cancer MDA-MB-231, and lung mesothelioma NCI-H226." (PMID 40943224, 2025). "EPHB2 activates bidirectional signaling cascades and its upregulation predicts poor survival in LUAD, CRC, breast cancer and malignant mesothelioma." (PMID 32102656, 2020). "Second, as our analysis shows, the prognostic value of EphB2 is strong in the luminal subtypes of breast cancer but not in basal or HER2-positive subtypes, all of which are known to have different biochemical and cellular characteristics." (PMID 34360867, 2021). "Especially EPHA2, EPHA4, EFNB1, EFNB2, EPHB2, and EPHB6 and their co-expression in breast cancer." (PMID 26870995, 2016). "The clinical role of EPHB2 in breast cancer is not well established." (PMID 26870995, 2016).
colon carcinoma (24 papers, 2006 to 2025). "High expression of EPHA4 but reduced expression of EPHB2 is linked with liver metastasis in human colon carcinomas, while high EPHA7 protein expression is associated with worse prognosis in patients with pancreatic cancer." (PMID 35204461, 2022). "This is exemplified by colon cancer, where EphB2, 3 and 4 are often overexpressed initially, and associated with stem-like self-renewal behavior, but can become lost during progression, promoting invasion and metastasis." (PMID 32397088, 2020). "Similarly, EphB2 and EphB3 deficiency in ApcMin/+ mice increased the frequency, size, and aggressiveness of colon tumours." (PMID 36830852, 2023). "Similarly, experiments in in vivo colon cancer models demonstrated that overexpression of EphB2 is associated with decreased perfusion and suppressed growth." (PMID 34943502, 2021). "The results suggest a limited role for these EPHB2 variants in colon tumor predisposition." (PMID 16740153, 2006). "Notwithstanding, germline EPHB2 variants do exist and may be associated with colon tumor predisposition, but further studies including functional analyses are needed to confirm this." (PMID 16740153, 2006). "Therefore, colon cancer progression is associated with a loss of EphB2 expression." (PMID 38391938, 2024). "EphB2 was found as one of the genes whose expression is increased in colon cancer cells resistant to platinum or taxane." (PMID 38391938, 2024). "The EphB4 expression relates with stage and grade of colon cancer, contrary to EphB2, whose expression is reduced with the tumor progression, and it is firstly abundant on colon progenitor cells." (PMID 32316101, 2020). "EphB2, also a member of the Eph family of receptor protein tyrosine kinases, has been extensively studied in colon cancer." (PMID 25148033, 2014). "Colon cancer cells with silencing of the tumor suppressor effects of EphB2 leads to invasive phenotype." (PMID 25148033, 2014). "The EPHB2 has a tumor suppressive role in colon carcinoma; in contrast, EPHB2 promotes cell proliferation in adenomas and normal intestinal epithelium." (PMID 22613809, 2011). "Overall, normal colonic mucosa showed a high level of EphB2 expression, which was maintained in colonic adenomas and significantly lower in CRC, suggesting that loss of EphB2 expression accompanies the progression of colonic neoplasms." (PMID 38651144, 2024). "Likewise, the EphB2 mAb 2H9 proved ineffective against fibrosarcoma and colon cancer xenografts when used as a naked antibody but was able to reduce tumour cell growth when fused to the auristatin MMAE." (PMID 36830852, 2023). "As regards EphB receptors, EphB4 and EphB2 showed an opposite expression in colon cancer cells." (PMID 32316101, 2020). "We hypothesized that EphB2 is expressed in normal bladder and lost in bladder cancer, similar to the observation in colon cancer, while induction of EphB4 in bladder cancer provides survival advantage." (PMID 25148033, 2014). "Sequencing analyses of paired tumor-normal genomic DNA samples revealed loss of the wild-type EPHB2 allele in the colon cancer from the proband, but not in the colon cancer from his father (data not shown)." (PMID 18682749, 2008). "Despite some promising results with a drug‐conjugated Ab raised against EPHB2, which is expressed in melanomas, neuroblastomas, gastric, lung, and colon cancers, which could induce cell death in EPHB2 expressing cells both in vitro and in vivo, no clinical data has been reported yet." (PMID 32337793, 2020). "Strikingly, most of the Wnt genes upregulated by HMGA1 in our murine model are also upregulated in human colon cancer, including the WNT effectors, ASCL2, AXIN2, CTNNB1, MYC, EPHB2, CD44, and ETS2 and the WNT receptors, LGR5, LRP5, and LRP6." (PMID 39895630, 2025). "Recently, a signature that predicts disease relapse in colon cancer in man was developed based on mouse intestinal stem cells (ISC) expressing high levels of the Lgr5 and EphB2 genes." (PMID 24069241, 2013).
colon carcinoma (continued). "In recent years, CSCs have been successfully purified from human colon cancers by employing different cell surface markers such as CD133, EpCAM, CD44 and CD166, and EphB2." (PMID 24069241, 2013). "Moreover, PAF1 knockdown decreased the expression levels of the genes such as LGR5, ID1, ID3, CD44v9, CD133, BMI1, RNF43, EPHB2, SOX9, and ASCL2, which are critical for inducing colon cancer stemness and its markers." (PMID 38182897, 2024). "Also, analysis of paired normal colon tissue and colon cancer (n = 26) showed that mRNA levels of EphB2, EphB3, EphB4, and EphA4 are significantly lower in the normal tissue than in the adjacent cancer, whereas levels of EphrinB2 and EphB1 are similar." (PMID 31545551, 2019). "This response was strongest for ephrin-B1 +EphB2 and ephrin-B1 + EphB3 with the response from ephrin-B1 and EphB4 only producing minor modifications in cell distribution and compartmentalization in the DLD1 colorectal adenocarcinoma and Co115 colon carcinoma cells lines used in that study." (PMID 20624275, 2010). "For colon cancer, CSCs have been isolated with non-uniform surface markers, including CD133, Lgr5, EpCAM, CD44, CD166, ALDH, and EphB2." (PMID 34621019, 2021). "Commonly repressed genes included the colon and colon cancer stem cell genes ASCL2 and LGR5 as well as EPHB2, SOX4 and P21, all as compared with control cells after normalization with housekeeping genes." (PMID 24920608, 2014). "Similarly the antagonist EphB2 mAb 2H9 did not inhibit tumor cell proliferation as a naked antibody, but when conjugated to the auristatin MMAE it was effective in inhibiting growth of fibrosarcoma and colon cancer xenografts." (PMID 32397088, 2020).
gastric cancer (20 papers, 2003 to 2025). A primary or metastatic malignant neoplasm involving the stomach. "For instance, high expression of PLIN3 and EPHB2 is associated with macrophage infiltration and poor response to immunotherapy in gastric carcinoma and other solid tumors." (PMID 41188771, 2025). "A gastric tissue microarray was used to investigate the association of the EphB2 protein expression with gastric cancer by immunohistochemistry." (PMID 32226496, 2020). "A complete loss of EphB2 expression is observed in 52.5% of gastric cancer and 82% of nodal metastases patients." (PMID 24959213, 2014). "Besides, EPHB2 mutations are closely associated with tumor suppression in gastric cancer and involved in the prognosis and metastasis of other tumors such as Ewing sarcoma." (PMID 35252170, 2022). "For example, a study on gastric cancer (GC) showed that as the tumor grade increased, the expression rates of EPHB2 lowered significantly, and the loss of EPHB2 expression was significantly associated with poor survival of GC patients." (PMID 37685904, 2023). "For instance, EPHB2 is highly expressed in hepatocellular carcinoma, lung adenocarcinoma, gastric cancer, and CRC but lowly expressed in esophageal cancer and squamous cell carcinoma of the skin." (PMID 41551156, 2025). "CDX2 up-regulated the expression of receptor tyrosine kinase EphB2 and reduced the migration of gastric cancer cells." (PMID 39768557, 2024). "EPHB2 is overexpressed in gastric cancer cells, and EPHB2 activation enhances the malignant properties of gastric cancer cells by reducing adhesion, accelerating migration and invasive ability." (PMID 37023088, 2023). "The functional role of EphB2 was determined using gastric cancer cells following CRISPR-mediated EphB2 gene expression activation." (PMID 32226496, 2020). "We found that expressions of eph (ephA1) and hek5 (ephB2) were upregulated following treatment in several gastric cancer cell lines." (PMID 12671705, 2003). "HPV capsid proteins L1 and L2 may induce virus internalization, probably through the attachment to neurogenic locus notch homolog protein 3 (NOTCH3) or EPH receptor B2 (EPHB2) in gastric cancer." (PMID 39228892, 2024). "Meanwhile, EphB2 activation accelerates both the migration and invasion of gastric cancer cells." (PMID 32226496, 2020). "In the current study, we attempted to investigate the clinical relevance in GC and the effect of EphB2 expression on gastric cancer (GC) cells." (PMID 32226496, 2020). "Specifically, F. nucleatum has been shown to enhance exosome production in gastric cancer cells, which in turn increases HOTTIP expression and facilitates gastric cancer invasion via the miR-885-3p/EphB2/PI3K/AKT signaling pathway." (PMID 39948481, 2025). "EPHA1, EPHA2, EPHA3, EPHA5, EPHB2 and EPHB4 expression has been reported as 2-fold higher in stromal cells isolated from gastric cancer tissues compared with normal gastric tissue stromal cells." (PMID 34445116, 2021). "EphB2 was found to be overexpressed in gastric cancer (GC) tissues than in adjacent or benign non-cancerous gastric tissues, including gene and protein expression." (PMID 35223830, 2022). "Nevertheless, EphB2-positive gastric cancers had a better prognosis than EphB2-negative cancers." (PMID 39768557, 2024). "The frequent deletion and decreased expression of EphB2 indicates that it may be a negative biomarker for gastric cancer and a potential predictor of the final outcome." (PMID 24959213, 2014). "Additionally, a recent study from China has identified that F. nucleatum-infected gastric cancer (GC) cells produce exosomes that increase the expression of the long non-coding RNA (lncRNA) HOXA transcript at the distal tip (HOTTIP), promoting GC invasion through the miR-885-3p/EphB2/PI3K/AKT axis." (PMID 38667331, 2024).
glioma (15 papers, 2013 to 2025). A benign or malignant brain and spinal cord tumor that arises from glial cells (astrocytes, oligodendrocytes, ependymal cells). "At the same time, overexpression of EphB2 in glioma tissues and cells inhibited cell adhesion and promoted cell invasion, indicating that the overexpression of EphB2 promotes tumor progression via forward signaling." (PMID 35223830, 2022). "High expression of EphB2 can reduce adhesion and increase the migration and invasion of glioma cells." (PMID 35448036, 2022). "overexpression of EphB2 inhibited cell adhesion and promoted cell invasion in glioma tissues and cells." (PMID 35223830, 2022). "Mechanistic investigations demonstrated that epigenetic silencing of miR-204 increased EphB2 expression in glioma cells and promoted EphB2-mediated invasion and migration." (PMID 35223830, 2022). "EphB2 expression was reported to be significantly higher in gliomas than in normal brain tissues and was correlated with tumor grade." (PMID 35223830, 2022). "On the other hand, it has also been reported that migrating glioblastoma (GBM) cells express high levels of EphB2 in vitro and in vivo, and that EphB2 overexpression in glioma cells results in increased cell invasion." (PMID 34360867, 2021). "EphB2 is posttranscriptionally regulated by miR-204, which is downregulated in both glioma cells and neural stem cells." (PMID 29682554, 2018). "Given the ability of miR-204 to target SOX4, it is suggested that altered abundances of SOX4 and EphB2 together are involved in modulating stemness and migration of glioma cells." (PMID 29682554, 2018). "First, miR‐204 targets EphB2 in glioma cells and regulates retinal axon guidance through Efnb3 (ephrin ligand) and EphB2 (receptor) during eye development in medaka." (PMID 26799631, 2016). "The increased propensity of ephrinB2 KO gliomas for diffuse invasion in a parenchymal environment was corroborated by co-cultivation with normal brain astrocytes expressing the ephrinB2 receptors EphB2 and EphB4." (PMID 27470974, 2016). "Notably, ephrin-B3 is essential for EphB2/Fc-induced invasion, reinforcing its role in glioma cell motility." (PMID 41200151, 2025). "EphB2 is overexpressed in glioma cells and plays a central role in tumor invasion and migration." (PMID 41200151, 2025). "CircMELK could upregulate EphB2 expression by sponging miR-593, thereby promoting the proliferation, invasion, migration, and glioma stem cell (GSC) maintenance of GBM cells." (PMID 35223830, 2022). "Gliomas derived from GIC overexpressing EphB2 have a high invasive potential." (PMID 35448036, 2022). "Similarly, EphB2, by interacting with either ephrin-B1 or ephrin-B3, stimulates invasion in glioma cells." (PMID 34360867, 2021). "Furthermore, downregulation of miR-204, which was found to be associated with gliomas in our study, was also proved to contribute to glioma migration by targeting the migration-promoting receptor EphB2." (PMID 24053158, 2013). "It inhibits the stem cell-like phenotype and migration of glioma cells by targeting SOX4 and EphB2, key regulators of migration and stem cell-related traits." (PMID 39633507, 2024). "When MELK is upregulated in GBM, EphB2 will be upregulated and promote EMT and glioma stem cell (GSC) maintenance." (PMID 36338770, 2022). "In addition to ependymoma, other gliomas, such as glioblastoma multiforme (GBM), overexpress EphB2; it would be interesting to ascertain if a similar mechanism of EphB2-mediated transformation is involved in their development as well." (PMID 25801123, 2015).